LAG3 (lymphocyte activating 3)
Diseases named in the same sentence as LAG3 in open-access papers (continued):
Sharing a sentence is not in itself a finding about the gene and the disease.
Parkinson disease (11 papers, 2018 to 2025). A progressive degenerative disorder of the central nervous system characterized by loss of dopamine producing neurons in the substantia nigra and the presence of Lewy bodies in the substantia nigra and locus coeruleus. "Specific single-nucleotide polymorphisms (SNPs) of the LAG3 gene have been also related to Parkinson’s disease occurrence especially in the female population." (PMID 40536592, 2025). "LAG3 has been implicated in the pathogenesis of Parkinson’s disease by mediating neuron-to-neuron transmission of misfolded preformed fibrils (PFF) of α-synuclein." (PMID 38556085, 2024). "More recently, it was proposed that LAG3 may function in the central nervous system (CNS) as a receptor of pathogenic α‐synuclein assemblies, which are causally involved in Parkinson’s disease (PD)." (PMID 34309222, 2021). "Several variants in the LAG3 and CD4 genes have been associated with the risk for multiple sclerosis (rs1922452 A > G) and Parkinson’s disease." (PMID 39769168, 2024). "None of the genes in this cluster have yet been curated into an aging database or connected to an age-related disease, although a recent report suggests a connection of LAG3 to Parkinson’s disease." (PMID 29270911, 2018). "The importance of LAG3 as an immune checkpoint on both effector T cells and regulatory T cells has been demonstrated in multiple disease models, including type 1 diabetes, Parkinson’s disease, allogeneic bone marrow transplant, and cancer." (PMID 38556085, 2024). "However, the interactions of LAG3 with its ligands and consequent signaling cascades, specially the recently discovered α-synuclein fibrils (α-syn), which seems to play a role in Parkinson’s disease, are not yet fully understood." (PMID 38233492, 2024). "Finally, we have investigated the impact of LAG3 on survival in ASYNA53T transgenic mice (a model of Parkinson’s disease) expressing wild‐type LAG3 as well as hemizygous or homozygous deletions thereof." (PMID 34309222, 2021). "In addition, a study has shown that LAG3 binds preformed fibrils of α-synuclein in the central nervous system, thereby promoting the pathogenesis of Parkinson’s disease in a mouse model, suggesting that LAG3 may also have functions outside the immune system." (PMID 35958563, 2022).
prostate carcinoma (11 papers, 2018 to 2025). A carcinoma that arises from epithelial cells of the prostate gland. "It was also observed that exhausted progenitors [CD8+PD-1+TCF1+ TIM-3(−) LAG-3(−)] were the cell subtype seen at higher rates in immunogenic prostate cancer." (PMID 36077354, 2022). "High LAG-3 expression in peripheral blood T cells and tumor-infiltrating lymphocytes correlates with histological signs of malignancy in prostate cancer." (PMID 36077354, 2022). "The combination of anti-PD-1-CTLA4 in the treatment of prostate cancer is gratifying; meanwhile, antagonizing LAG3 and PD1 can enhance tumor-specific cellular response and induce tumor rejection." (PMID 33215029, 2020). "Therefore, we explored the expression of inhibitory receptors in CD8+ T cells in prostate cancers including PD-1, LAG3, TIM-3, TIGIT, and BTLA." (PMID 32850758, 2020).
colon adenocarcinoma (10 papers, 2018 to 2025). "Simultaneous blockade of PD-1 and LAG-3 synergizes to enhance anti-tumor CTLs activity and reduces tumor growth in a colon adenocarcinoma model, a chronic lymphocytic leukemia (CLL) model, and a malignant pleural mesothelioma model." (PMID 35164813, 2022). "Simultaneously targeting TIM-3 and PD-1 increases LAG-3 expression in TILs, suggesting a cross-regulation between IC receptors, and triple blockade of TIM-3, PD-1, and LAG-3 results in reduced tumor growth in a colon adenocarcinoma model." (PMID 35164813, 2022). "Another inhibitory receptor expressed on activated CD4 and CD8 T cells is LAG-3 and various studies have suggested that anti-LAG-3 and anti PD-1 treatment cured mice with established colon adenocarcinoma and fibrosarcoma tumors." (PMID 30853982, 2019). "Notably, higher expressions of CTLA4 and PD1 were associated with improved survival, while higher TIL load correlated with CTLA4, HAVCR2 (TIM-3), LAG3, and CD274 (PD-L1) expressions in colon adenocarcinoma." (PMID 35804964, 2022).
fibrosarcoma (10 papers, 2015 to 2025). A malignant mesenchymal fibroblastic neoplasm affecting the soft tissue and bone. "They studied the dual blockade of LAG-3/PD-1 and tumor response in Sa1N fibrosarcoma and MC38-colorectal adenocarcinoma-inoculated mice." (PMID 37999131, 2023). "Whereas treatment with anti-LAG-3 alone or anti-PD-1 alone delayed tumor growth in a minority of treated mice (0–40%), dual therapy with anti-LAG-3 and anti-PD-1 resulted in complete tumor regression in 70 and 80% of mice with fibrosarcoma and colorectal tumors, respectively." (PMID 26881264, 2016).
multiple sclerosis (10 papers, 2019 to 2024). A progressive autoimmune disorder affecting the central nervous system resulting in demyelination. "LAG3 rs2365095 has been found to be associated with multiple sclerosis in the Jordanian Arab population." (PMID 35265454, 2022). "It has been reported that the polymorphisms of LAG3 rs19922452, rs951818, and rs870849 genes are related to the susceptibility to multiple sclerosis, and rs19922452 TT, rs951818 GG, and rs870849 CT genotypes were significantly associated with decreased risk of multiple sclerosis." (PMID 37131179, 2023). "A similar explanation may be applied to the LAG3 SNP used in the present study, rs870849, which was previously shown to be associated with multiple sclerosis." (PMID 34206082, 2021). "Several recent works have raised the possibility of the contribution of the lymphocyte activation gene 3 (LAG3) protein in the inflammatory processes of multiple sclerosis (MS)." (PMID 36499569, 2022). "Till now, there was no investigation to explore the possible influence of LAG3 variants on the Chinese PD population, although there were three variants of LAG3 such as rs1922452, rs951818, and rs870849 were identified as a potential risk factor to multiple sclerosis (MS)." (PMID 31847878, 2019). "Interpretation: This is an initial exploration of the utility of CTLA-4, PD-1, TIM-3, LAG-3, and TIGIT expression levels as prognostic indicators in untreated, recently diagnosed multiple sclerosis." (PMID 31134049, 2019). "LAG-3 levels were significantly higher in patients with low disability index vs. non-low disability index multiple sclerosis (P < 0.05)." (PMID 31134049, 2019).
myocarditis (10 papers, 2016 to 2026). Myocarditis is a condition that is characterized by inflammation of the heart muscle (myocardium). "In a phase 3 study with a LAG-3 inhibitor (Relatlimab) in association with a PD-1 inhibitor (nivolumab), myocarditis occurred in 1.7% of the patients." (PMID 39225869, 2025). "Although LAG-3-associated myocarditis is rarely seen, few cases of myocarditis have been reported when administered with anti-LAG-3 agents." (PMID 40255399, 2025). "Anti‐LAG3 molecule comes with an increased risk of cardiac irAE, especially myocarditis." (PMID 41473819, 2025). "Furthermore, compared with LAG-3 deficiency alone, dual knock out of LAG-3 and PD-1 has been found to quickly induce lethal myocarditis on the BALB/c mice model." (PMID 30603054, 2018). "Recent clinical trials examining the combination of relatlimab (an anti-LAG-3 monoclonal antibody) and nivolumab (an anti-PD-1 monoclonal antibody) have shown a slight increase in the incidence of myocarditis." (PMID 40606990, 2025). "Corroborating this, it was demonstrated that Lag3−/− Pdcd1−/− mice exhibited an early-onset lethal autoimmune condition, manifesting with endocarditis, myocarditis, and pancreatitis." (PMID 39039301, 2025). "The incidence of myocarditis with the use of antilymphocyte antigen 3 (LAG3) agents is higher than previously thought." (PMID 41473819, 2025). "In the context of cardiovascular diseases, including atherosclerosis and myocarditis, LAG-3 may serve to modulate the inflammatory response, reducing the risk of autoimmune damage to the heart." (PMID 40255399, 2025). "In the RELATIVITY-047 clinical trial carried out on more than 700 subjects, 1.7% of the subjects reported developing myocarditis when administered a blend of relatlimab (LAG-3–blocker) –nivolumab (PD-1 inhibitor) as against 0.6% of the subjects that received monotherapy of nivolumab only." (PMID 40255399, 2025). "However, when both LAG-3 and PD-1 were knocked out, a lethal form of myocarditis emerged, characterized by T-cell infiltration, heightened secretion of tumor necrosis factor (TNF), and persistent inhibitory function of Tregs." (PMID 38375475, 2024). "However, knockout of both LAG-3 and PD-1 led to the development of lethal myocarditis with T-cell infiltration and increased TNFα secretion but sustained repressive Treg function, emulating trends from human clinical trials." (PMID 36263134, 2022). "Similarly, combined anti-PD-1/anti-LAG-3 therapy in recent trials reported somewhat higher numbers of myocarditis as compared to single anti-PD-1 therapy (1.7 vs. 0.6%, respectively)." (PMID 36263134, 2022). "However, studies in the knockout model that was devoid of LAG-3 as well as PD-1, exhibited the development of myocarditis along with elevated levels of TNF-α and excessive infiltration of Thymocytes, though Treg cells exhibited a controlled functioning in such animals." (PMID 40255399, 2025). "Similarly, recent trials involving combined nivolumab (anti-PD-1 mAb) and relatlimab (anti-LAG-3 mAb) therapy revealed slightly elevated instances of myocarditis in comparison to the usage of single nivolumab (anti-PD-1 mAb) therapy (1.7% versus 0.6%, respectively)." (PMID 38375475, 2024). "Previous LAG-3-related animal research has demonstrated that mice lacking LAG-3 did not develop myocarditis." (PMID 40606990, 2025). "Studies in knockout animal models that are devoid of LAG-3 also point out to lack of relation between LAG-3 and myocarditis." (PMID 40255399, 2025). "To date, no cases of myocarditis have been explicitly attributed to LAG-3 inhibition." (PMID 41598751, 2026). "In clinical trials and post-marketing data, the safety profile of relatlimab—currently the only approved LAG-3 inhibitor—does not show an increased incidence of myocarditis beyond that observed with PD-1 blockade, and no myocarditis events have been reported with other investigational LAG-3 agents." (PMID 41598751, 2026).
myocarditis (continued). "However, when both LAG-3 and PD-1 were lacking, a severe type of myocarditis developed that was marked by T-cell infiltration, increased production of tumor necrosis factor (TNF), and persistent Treg inhibitory activity." (PMID 40606990, 2025). "In animal experiments focusing on LAG-3, it has been previously documented that the knockout of LAG-3 in mice did not result in the onset of myocarditis." (PMID 38375475, 2024). "As LAG-3 is only recently FDA approved, not many cases on ICI-mediated myocarditis have been reported yet." (PMID 36263134, 2022).
type 1 diabetes (10 papers, 2016 to 2025). "Furthermore, reduced s-LAG3, suggesting decreased LAG3 cleavage, was associated with inhibition of type 1 diabetes after treatment." (PMID 33488573, 2020). "s-LAG3 might be an early T-cell-specific biomarker for type 1 diabetes onset." (PMID 33488573, 2020). "In a murine model of Type 1 diabetes, signaling through LAG-3 was shown to limit TREG function and it is unclear if antagonistic antibodies that prevent LAG-3 signaling could enhance TREG suppressive function at the same time that they are promoting effector T cell activity." (PMID 32299365, 2020).
esophageal cancer (9 papers, 2019 to 2025). A primary or metastatic malignant neoplasm involving the esophagus. "We also detected several other co-inhibitory molecules (PD-1, TIGIT, and LAG-3) on the surface of NK cells in 5 esophageal cancer patients." (PMID 31109341, 2019). "In a clinical trial of advanced esophageal cancer treated with pembrolizumab (anti PD-1) as ≥ second-line therapy, gene expression profiling revealed co-enrichment of LAG3 and IDO1 in PD-L1+ tumors, and high LAG-3 expression was associated with poorer progression-free survival." (PMID 40787471, 2025). "Moreover, our study indicates that EBV and cytomegalovirus elevate PD-L1 or PD-L2, CD80, CD86, PD-1, CTLA-4, Tim-3, LAG3, and 4-1BB expression in multiple cancers along the gastrointestinal tract including stomach and esophageal carcinoma and colon and rectum adenocarcinoma." (PMID 30911684, 2019). "Recent advances in cancer immunotherapy extend beyond PD-1/PD-L1 blockade to include novel checkpoint targets (e.g., LAG-3, TIGIT), engineered cellular therapies, and strategies to remodel the tumor microenvironment (TME)—strategies increasingly relevant to esophageal cancer." (PMID 40842543, 2025).
HIV-1 infection (9 papers, 2015 to 2025). The type species of lentivirus and the etiologic agent of acquired immunodeficiency syndrome (AIDS). "The role of Lag-3 (CD223) in HIV-1 infection is less clear, although its upregulation has been associated with disease progression and functional T-cell exhaustion." (PMID 26449164, 2015). "In HIV-1 infection T cell exhaustion is associated with the up-regulation of surface molecules called immune checkpoint receptors (ICRs) such as PD-1, Tim-3 and Lag-3, which have also been associated with the size of the HIV reservoir and time to viral rebound after therapy cessation." (PMID 27415828, 2016). "We, therefore, explored whether these markers were co-expressed with Tim-3, Lag-3 and PD-1 in early HIV-1 infection in the HEATHER cohort." (PMID 27415828, 2016). "A study reported that genome editing of CXCR4 and CCR5 using CRISPR-Cas9 prevented HIV-1 infection in CD4+ T cells by affecting the inhibitory receptors of T cells, like PD-1 and Lymphocyte Activation Gene-3 (LAG3)." (PMID 41394966, 2025). "An upregulated expression of various ICMs including PD-1, CTLA-4, TIM-3, LAG-3, and TIGIT has been reported in HIV-1 infection." (PMID 40872312, 2025). "Similarly, we found rapid increases of KLRG1, LAG-3, PD-1, and TIGIT expression in blood and tissue NK cells within 2 weeks after HIV-1 infection." (PMID 36282589, 2022). "PD-1, CTLA-4, TIM-3, LAG-3 and, TIGIT on both CD4+ and CD8+ T-lymphocytes in the peripheral blood of treatment-naïve individuals from four cohorts, including active pulmonary tuberculosis (TB), HIV-1 infection only, HIV-TB co-infected, and healthy volunteers from North India." (PMID 40872312, 2025). "Intriguingly, ex vivo neutralization of miR-146a in PBMCs from chronic HIV-1 infection exhibited an elevated antiviral cytokines production as well as the expression of GZMB and perforin, while simultaneously, decreased the inhibitory receptors expression such as PD-1, CTLA-4, TIM-3 and LAG-3." (PMID 31827152, 2019). "The role of Lag-3 in HIV-1 infection is not yet fully elucidated and data are conflicting." (PMID 27415828, 2016).
lupus (9 papers, 2015 to 2022). "We previously verified that polymorphisms in EGR2 are associated with susceptibility to SLE, and that Egr2 is characteristically expressed in LAG3+ Tregs, which have the potential to ameliorate lupus pathology." (PMID 30071700, 2018). "Recently, we reported that secretion of TGF-β3 by LAG3+ Tregs is regulated by LTBP-3 in T cells in a murine model of lupus." (PMID 30071700, 2018). "The association between Egr2 and autoantibody-mediated systemic autoimmunity suggested a linkage between Egr2-expressing LAG3+ Tregs and the control of lupus activity." (PMID 29535721, 2018). "Three-time injections of MRL/+LAG3+ Tregalso ameliorated lupus pathologies in MRL/lpr mice after the onset of overt proteinuria." (PMID 25695838, 2015). "In MRL/lpr lupus-prone mice, adoptive transfer of LAG3+ Treg from MRL/+ micesuppresses the progression of lupus in a TGF-β3-dependent manner." (PMID 25695838, 2015). "While EGR2+ Fas+ LAG3+ Tregs were able to suppress lupus development in MRL-lpr mice, neither EGR2 or Fas deficient LAG3+ Tregs had autoimmune suppressive role." (PMID 32646370, 2020). "LAG3+ Treg require TGF-β3 to suppress B-cellresponses in a murine model of lupus." (PMID 25695838, 2015). "We investigated whether LAG3+ Treg were able to inhibit diseaseprogression in lupus-prone MRL-Faslpr/lpr(MRL/lpr) micewith a Fasmutation17." (PMID 25695838, 2015). "In patients with systemic lupus erythematosus (SLE), human immunodeficiency virus (HIV), or carotid artery stenosis, membrane LAG3 expression was also associated with the disease activity and disease progression." (PMID 36247429, 2022). "In lupus-prone MRL-Faslpr/lpr (MRL/lpr) mice, adoptive transfer of LAG3+ Tregs from control MRL-Fas+/+ (MRL/+) mice suppresses the progression of lupus in a TGF-β3-dependent manner." (PMID 29535721, 2018). "Furthermore, therapeutic effects of TGF-β3 in murine lupus, and the reduction of TGF-β3-secreting LAG3+ Tregs in SLE patients imply potential preventive roles of TGF-β3 in SLE." (PMID 30071700, 2018). "The results of the present study demonstrated that LAG3+ Treg suppress thedevelopment of GCB andTFH, antibody production and disease progression in lupus-proneMRL/lpr mice.TGF-β3, which isproduced by LAG3+Treg in Egr2- and Fas-dependent manners, plays a criticalrole in suppressing humoral immunity." (PMID 25695838, 2015).
rheumatoid arthritis (9 papers, 2017 to 2025). A chronic, systemic autoimmune disorder characterized by inflammation in the synovial membranes and articular surfaces. "We aimed to clarify the function of human IL-10-producing CD4+CD25−LAG3+ T cells (LAG3+ Tregs) and their association with rheumatoid arthritis (RA)." (PMID 28511719, 2017). "Lymphocyte activation gene-3 (LAG3) positive B cells have been identified as a novel regulatory B cell subset, while the role of LAG3+ B cells in the pathogenesis of rheumatoid arthritis (RA) remains elusive." (PMID 37143367, 2023). "As antigen presentation is central in rheumatoid arthritis (RA) pathogenesis, we studied aspects of LAG-3 as a serological marker and mediator in the pathogenesis of RA." (PMID 37287025, 2023).